E2F1 (E2F transcription factor 1)
Diseases named in the same sentence as E2F1 in open-access papers (continued):
Sharing a sentence is not in itself a finding about the gene and the disease.
cancer (continued). "Transcription of proteins essential for G1-S depends on E2F1-5 proteins and their dimerization partners (pRb, p107, and p130, encoded by RB1, RBL1, and RBL2 respectively); genes encoding these proteins are often dysregulated or mutated in cancer." (PMID 29725503, 2018). "Hence, the apoptosis of cancer cells is inhibited because the E2F1-activated apoptotic signaling pathway was blocked." (PMID 30235236, 2018). "This study explored the function of TFDP3 in cancer cell autophagy combining with E2F1." (PMID 30235236, 2018). "Interestingly, the collaboration of EZH2 and E2F1 in transcriptional regulation has been observed in various cancers." (PMID 28427185, 2017). "The authors suggested that the recruitment of Pontin and Reptin may be a common mechanism used by E2F1 to promote cancer progression." (PMID 28884116, 2017). "Finally, coming back to the pivotal role of E2F1 in cancer development, we discuss how E2F1 links cell cycle progression with different metabolic adaptations required for cell growth and survival." (PMID 29176962, 2017). "In contrast, our map sets a main focus on the newly discovered role of activating members of the E2F family (E2F1-3) in cancer development and progression, with an emphasis on pro-apoptotic and anti-apoptotic (survival), angiogenic as well as functions relevant for EMT." (PMID 28775339, 2017). "Alternatively, a better understanding of the molecular players may help in treating patients suffering from cancer as unexpected targets may be unveiled, allowing restoration of a proper Rb-E2F1 axis in cancer cells." (PMID 29048367, 2017). "Whether E2F1 promotes anabolic reprogramming in cancer cells through the interaction with these signaling pathways remain to be explored." (PMID 29176962, 2017). "Additionally, numerous studies have highlighted the crosstalk between E2F1 activity and other signaling pathways involved in cancer metabolism, such as the AKT or the HIF pathways." (PMID 29176962, 2017). "Since both Rb and E2F1 are regulated by ubiquitination, dysregulation of this post-translational modification could serve as a marker for cancer development." (PMID 29048367, 2017). "E2F1 plays a critical role in the malignant phenotypes of some cancers." (PMID 28947952, 2017). "E2F1 contributes to the metabolic reprograming of cancer cells." (PMID 29176962, 2017). "TS expression and E2F1 expression were seen in nuclei of cancer cells." (PMID 26831819, 2016). "If so, GCN5 and AIB1 may form an amplification circuit to up-regulate each other through cooperating with E2F1, leading to dramatically enhanced cancer cell cycle progression." (PMID 27486509, 2016). "Our results increase our understanding of the mechanisms through which the COX-2/EP1R/MAPK/E2F-1 pathways regulate β1-integrin expression and cancer invasion, and may guide the future development of therapeutic interventions." (PMID 27654511, 2016). "For example, while mTOR and E2F1 are the top-ranking oncomodules associated to mutations of MLL2 in HNSC, we found that oncomodules in the MEK/AKT1 axis are top-ranking in association to NSD1 mutations in the same cancer type." (PMID 27095575, 2016). "In addition, we also found that the L-FFL motif comprised of E2F1, miR-195 and SNHG12, and the L-FFL motif comprised of E2F1, miR-106b and KB-1732A1.1, were dysregulated in three types of cancers." (PMID 27322142, 2016). "Furthermore, it was postulated that between normal cell proliferation and onset of apoptosis is a range of oncogenic activity (of E2F1 or c-Myc) with significant probability of the cancer state; such a range is referred to as the ‘cancer zone’10." (PMID 27610602, 2016). "Targeting the COX-2/EP1/PKC/MAPK/E2F-1/FoxC2/β1-integrin pathway might represent a new therapeutic strategy for the prevention and treatment of this cancer." (PMID 27654511, 2016).
cancer (continued). "In contrast, carcinomas developed in Rbf/f;K14creERTM;E2F1−/− mice are predominantly located in body fur, display follicular origin without expression of interfollicular differentiation markers, have incomplete penetrance and slow progression with no overt signs of malignancy." (PMID 27708231, 2016). "Thus, the apoptotic activity of E2F1 is restrained in human cancer by the concomitant induction of EZH2 and Bim." (PMID 26405162, 2015). "Despite the impact of these processes on cancer progression, the molecular mechanisms by which E2F1 regulates these responses are still unknown." (PMID 26356814, 2015). "E2F1 pathways are commonly dysregulated in cancer, and increased TPIP expression in the presence of increased E2F1 expression in tumors could reflect dysregulation of TPIP transcription." (PMID 26230935, 2015). "Both miRNAs regulate cancer activity by targeting the same gene E2F1." (PMID 26273679, 2015). "In light of the established roles of E2F and NFY in cancer phenotypes, we sought to determine whether the transcriptional program jointly controlled by E2F1 and NFYB might define unique cancer states." (PMID 26039627, 2015). "In addition to promoting cell proliferation, E2F1 also regulates many genes involved in glycolysis which is essential for rapid growth of cancer cells." (PMID 26484566, 2015). "In summary, when considered together with data showing NFYB as protective against E2F1-mediated apoptosis, this analysis suggests that the joint E2F1/NFYB transcriptional program may play a role in cancer resistance to chemotherapy." (PMID 26039627, 2015). "A loss of FAF1 function could cause constitutive WNT pathway activity (consistent with the downstream inductions of IGF2BP1 and E2F1 in this cancer)." (PMID 25861239, 2015). "Furthermore, loss of E2F1 potentiated HPV-positive oral tumor growth and overexpression of E2F1 decreased the clonogenicity of HPV-positive cancer cells." (PMID 26670255, 2015). "However, when analyzing the data for the cancer cells independently, the reduction of the RB gene expression signature (z = −2.46) and activation of the E2F1 signature (z = 2.34) were confirmed, and activation of the AR signature (z = 2.99) was significant." (PMID 25575823, 2015). "Cancer cells with elevated E2F1 activity were highly sensitive to HDACi-induced cell death." (PMID 26405162, 2015). "Because TMCG/DIPY treatment modulates the methylation status/stability of E2F1, the results demonstrate that therapies targeting the epigenetic machinery of cancer cells in the presence of overexpressed E2F1 may result in efficient E2F1-mediated cell death." (PMID 25064027, 2014). "Furthermore, the mechanisms of CIP2A activation and overexpression in cancer cells has been investigated by several other studies in which E2F1, ETS1, and ATF2 were found to directly bind to the CIP2A promoter and further stimulate CIP2A transcription." (PMID 24884612, 2014). "As such, e2f-1 could play different roles at different stages of cancer; that is, it might promote the formation of the cancer in the early stages but inhibit the progression of cancer in the intermediate and advanced stages." (PMID 24393368, 2014). "The role of E2F1 in metastatic process was recently investigated in different cancer types." (PMID 24755270, 2014).
cancer (continued). "Interestingly, it has been reported that miR-29s target CCND2 in various cancer types and E2F1 in OS." (PMID 25174983, 2014). "Most importantly, E2F1 plays a critical role in the malignant phenotypes of some cancers." (PMID 25466554, 2014). "E2F-1 levels, as well as E2F-3 levels have been shown to be increased in several human cancers." (PMID 24658650, 2014). "E2F1 is an important downstream effector that mediates apoptosis in cancer cells." (PMID 24691157, 2014). "Since the relative chemoresistance of these carcinomas appears to be linked to high E2F7/E2F1 ratio, targeting CtBPs may enhance the expression of E2F1 and the apoptotic response." (PMID 24955216, 2014). "Moreover, E2F1 transfection was found to contribute significantly to cancer cell proliferation, migration and invasion in vitro." (PMID 24023875, 2013). "In conclusion, E2F1 activation mediated higher malignancy and vascular infiltration potential in ccRCC by promoting the proliferation, migration and invasion capacities of cancer cells." (PMID 24023875, 2013). "Transcription factor E2F1 exerts effects on many types of cancers." (PMID 24023875, 2013). "Given the statistical results we inferred that E2F1 may help cancer cell to penetrate Gerota’s fascia which constricted tumors locally, namely, metastatic process was evaluated." (PMID 24023875, 2013). "Down regulation of E2F1 enhances the sensitivity of chemotherapy of cancer cell." (PMID 24341432, 2013). "Moreover there is study that challenges classical concept of pRb in suppressing cancer via negative regulation of E2F1." (PMID 23773282, 2013). "Interestingly, the strongest eugenol inhibitory effect was observed on E2F1 and survivin, a cancer anti-apoptosis marker in both cell lines." (PMID 24330704, 2013). "Altogether, this work identifies the RIP140 gene as a new transcriptional target of E2F1 which may explain some of the effect of E2F1 in both cancer and metabolic diseases." (PMID 22629304, 2012). "It is therefore compelling to investigate whether EBNA3C can further regulate the function of E2F1; the downstream effector of this pathway in order to control proliferation of EBV associated cancer cells." (PMID 22438805, 2012). "Our data identify the RIP140 gene as a novel transcriptional target of E2F1 that might be involved in a wide range of pathological processes regulated by this transcription factor such as cancer or metabolic diseases." (PMID 22629304, 2012). "On the other hand, many cancers display increased levels of E2F1 and this may contribute to resistance against chemotherapeutics such as cisplatin." (PMID 23202967, 2012). "The E2F1 R166H somatic mutation is of particular interest as there is no reported mutation of the E2F1 gene in cancer." (PMID 21955916, 2011). "Although E2F1-R166H does not show a significant effect on regulating cell proliferation, it is possible that the mutation is advantageous to cancer cells as it does not inhibit cell growth when the mutant is highly expressed in cells." (PMID 21955916, 2011). "The members of the family E2F1, 2, 3 and E2F4 have been reported to be associated with cancer." (PMID 22041030, 2011). "Functional inactivation of pRB1 in various human cancers leads to deregulated E2F1 activity." (PMID 20976175, 2010). "With further development, shRNA against E2f1 may prove to be an interesting strategy in the treatment of proliferative diseases, such as cancer and other physiopathological conditions, including neointimal hyperplasia associated to cardiovascular derangements." (PMID 21637599, 2010).
cancer (continued). "Based on the positive role of Sei1 on Cdk4/D and E2f1 activities, it is conceivable that Sei1 could have a role in cancer and/or pancreatic islet biology." (PMID 20090907, 2010). "Therefore, to determine if E2F-1 can completely repress hTERT transcription, the E2F-1 protein must be effectively transduced into 100% of the cancer cells." (PMID 18366791, 2008). "Therefore, the regulatory module starting on E2F1 TF shows the chain processes of the regulatory mechanism, which implies the complication of human cancer-related regulatory manipulations." (PMID 17359522, 2007). "The E2F-1 is a member of the E2F family that is found to be elevated in cancer cells." (PMID 12838312, 2003). "Although targeting RB1 loss or E2F1 has long been considered a promising strategy for cancer therapy, currently, there are no agents that directly target RB1/E2F1 in the market due to their undruggable characteristics as well as their general roles in biological processes in the healthy body." (PMID 41492471, 2026). "Therefore, in theory, the presence of distinct E2F1 activity may serve to discriminate cancer cells from normal growing cells." (PMID 41511373, 2026). "However, whether the distinct regulation of the tumor suppressor genes by E2F1 also exists in other cell types, especially epithelial cells, from which 90% of cancers arise, has yet to be determined." (PMID 41511373, 2026). "E2F1 is the most widely studied member of the E2F family which, through its control by the retinoblastoma protein (pRb), is important in the regulation of cell cycle progression in diverse cell types, with deregulation of the pathway being one of the hall marks for cancer." (PMID 39021294, 2025). "Hence, it is expected that utilizing deregulated E2F activity using ARF and TAp73 promoter elements provides an advantage over enhanced E2F activity in cancer cells and growth-related E2F target promoters such as E2F1, which shows high activity in normally growing cells." (PMID 41439972, 2025). "Besides, PSMD14 could also stabilize E2F1, which enhanced E2F1 target gene expression and cancer progression in head and neck squamous carcinoma." (PMID 38017133, 2024). "The authors argue that this effect could be explained by increased expression of cyclin B and a reduced expression of cyclin D, E2F1, cyclin E, and E2F2 and thus, conclude that QRC reduced the number of viable cancer cells by this mechanism that is associated with apoptosis." (PMID 38398890, 2024). "Fully deciphering the intricate network of lncRNA/E2F1-mediated regulatory mechanisms in cancer could facilitate the translation of current findings into clinical course, such efforts ultimately significantly improve the clinical prognosis of cancer patients." (PMID 39119602, 2024). "Interestingly, we found that overexpression of HSPB6 based on E2F1 overexpression could inhibit the cancer-promoting ability of E2F1." (PMID 38374143, 2024). "Similarly, high expression of E2F1 promotes the occurrence and progression in other cancers." (PMID 37497116, 2023).
cancer (continued). "Therefore, the identification of novel small molecules targeting the E2F1/Rb/HDAC1 complex may provide a more effective therapeutic strategy for cancer." (PMID 38062013, 2023). "Therefore, cancer cells harbor deregulated E2F1 activity, which activates the ARF gene." (PMID 36833320, 2023). "Interestingly, E2F1 was highly expressed in most cancer types." (PMID 37497116, 2023). "The cyclin dependent kinase 4 (CDK4)-pRB-E2F1 axis has been shown to be essential for cell cycle progression in normal and cancer cells, and high expression of E2F1 has been found to promote the proliferation of cancer cells by transactivating cell cycle-related kinases." (PMID 36221072, 2022). "Thus, E2F1 could promote cancer proliferation via upregulating POLD2 expression in TNBC, indicating that the E2F1-POLD2 signaling pathway is a driver of TNBC proliferation and could be a potential therapeutic target for the treatment of TNBC." (PMID 36119494, 2022). "Thus, targeting this PPI might be reasonable to complement standard anti-angiogenic treatment of cancers with deregulated E2F1 and can play a role in drug repurposing (see Section 7)." (PMID 36678712, 2022). "Moreover, multiple studies have revealed the critical roles of E2F1 in cancer progression." (PMID 36414640, 2022). "Given the clinical and functional significance of KAT2A/E2F1/UBE2C in pan-cancer, we concluded that KAT2A/E2F1/UBE2C and its associated pathway were crucial for cancer carcinogenesis, and targeting this pathway may be pivotal in the prevention or treatment of pan-cancer." (PMID 36292703, 2022). "Moreover, KAT2A and E2F1 could promote cell proliferation and the migration of cancer cells by enhancing the expression of UBE2C." (PMID 36292703, 2022). "Avasimibe could also suppress PCa cell proliferation by downregulating the expression of low-density lipoprotein receptors and decreasing low-density lipoprotein uptake; this is also one of the pathways through which the E2F-1 protein exerts its anti-cancer effects." (PMID 34461908, 2021). "Because EZH2 was documented to physically interacts and cooperate with E2F1 to stimulate the expression of a group of genes involved in cancer progression, we thus tested by co-immunoprecipitation whether such an interaction occurs in four different PAH-PASMC cell lines." (PMID 33803922, 2021). "Besides, a previous study showed that E2F1 could be a common marker gene of cell proliferation in various cancers." (PMID 34650921, 2021). "Therefore, E2F1 is expected to become a new target for cancer treatment." (PMID 33070516, 2020). "Thus, cdk4, cdk6, e2f1, and rb1 not only participate in the progression of cancer cells but might also be useful biomarkers for predicting prognosis in some tumors." (PMID 32357912, 2020). "Cancers displaying unfavorable risk with high ALT (BRCA, SARC, and LUAD) may be regulated by the transcriptional factors E2F4, TFDP1, E2F1, E2F7, and SIN3A (FDR = 0.001) in the DNA repair pathway, including genes repairing DNA damage such as CENPI, CLSPN, TOPBP1, and MCM4." (PMID 32784588, 2020). "Besides, evidence has proved that E2F1 related to cancer metastasis." (PMID 31934717, 2020). "It has been reported that E2F1 may promote DNA replication and cancer cell proliferation." (PMID 33023042, 2020).